HMGB1 (high mobility group box 1)
Diseases named in the same sentence as HMGB1 in open-access papers (continued):
Sharing a sentence is not in itself a finding about the gene and the disease.
dengue (continued). "HMGB1, working in a pro-inflammatory context and with strong implications in altered vascular permeability, would end up leading to a scenario that is favorable to the progression of dengue disease." (PMID 29167501, 2017). "In addition, the plasma level of HMGB1 was proposed as a predictive marker of traumatic brain injury and the disease outcome of dengue virus infection." (PMID 23874584, 2013). "DHF/DSS appears late in dengue illness and HMGB1 may have a role in the progression of DHF/DSS by affecting vascular integrity as well as the secretion of other host cytokines." (PMID 22860034, 2012). "The release of HMGB1 protein may take place early in the intracellular life cycle of the DV and may also mediate the symptoms of dengue fever." (PMID 22860034, 2012). "Therefore, EP was investigated for its ability to inhibit HMGB1 release from dengue-infected K562 and PBM cells." (PMID 22860034, 2012). "High concentrations of HMGB1 have been detected in patients with several infectious diseases, including dengue, and it could be considered as a biomarker for the early diagnosis of dengue and a predictor of complications of the disease." (PMID 36016387, 2022). "In this regard, HMGB1 could contribute to the immunopathogenesis of dengue, enhancing CNS symptoms." (PMID 32486462, 2020). "Based on these reports, it would be reasonable to suggest that the HMGB1-mediated signaling combined with DENV NS1 influence (or also with other potential viral antigen) may represent a key consolidation factor for the progression of dengue disease." (PMID 29167501, 2017). "Previous studies have reported the roles of HMGB-1 and ICAM-1 in dengue virus infection where both proteins were released by dengue infected endothelium or immune cells and increased permeability of endothelial cells leading to vascular leakage." (PMID 32764789, 2020). "In this work, we investigated the participation of high mobility group box 1 (HMGB1), an important modulator of inflammation, in dengue fatal cases." (PMID 29167501, 2017). "While non-dengue lung samples exhibiting regular structure of the alveolar septum presented only a marginal expression of nuclear HMGB1, in severe dengue samples, which presented alveolar septal thickening, we could observe numerous resident macrophages expressing cytoplasmic HMGB1." (PMID 29167501, 2017). "In this study, the release of HMGB1 from human myelogenous leukemia cell line K562 and primary peripheral blood monocytes (PBM) cells was examined during dengue virus (DV)-infection." (PMID 22860034, 2012). "The findings presented in this review support the hypothesis that HMGB1 is involved in DENV pathogenesis and could be a potential marker for diagnosing and managing dengue cases." (PMID 36016387, 2022). "The mean concentration of HMGB-1 was highest in patients with SD, however, the difference in expression between HC and dengue cases were not significant, making the role of this cytokine in dengue pathogenesis inconclusive." (PMID 32764789, 2020). "All non-dengue controls (liver, lung and heart tissues) were negative for dengue-RNA and showed marginal expression of HMGB1 predominantly within the nuclear regions." (PMID 29167501, 2017). "Results from a semi-quantitative analysis revealed that the number of cells expressing cytoplasmic HMGB1 was statistically increased in lung and heart tissues of all four dengue fatal cases, as compared to non-dengue controls." (PMID 29167501, 2017). "Subsequently, as determined by immunohistochemistry (IHC), all these analyzed sites (liver, lung and heart) from dengue fatal cases showed increased expression of cytoplasmic HMGB1, when compared to non-infected controls." (PMID 29167501, 2017). "Further experiments of immunohistochemistry (IHC) showed increased expression of cytoplasmic HMGB1 in dengue-extracted tissues when compared to non-dengue controls." (PMID 29167501, 2017).
dengue (continued). "Therefore, the same authors evaluated serum HMGB1 levels in 205 samples from adult individuals with dengue-like fever (DLF), non-laboratory-confirmed clinical cases of dengue (CC), and healthy blood donors as the negative control." (PMID 36016387, 2022).
diabetic neuropathy (12 papers, 2017 to 2024). A chronic, pathological complication associated with diabetes mellitus, where nerve damages are incurred due to diabetic microvascular injury involving small blood vessels that supply these nerves, resulting in peripheral and/or autonomic nerve dysfunction. "Indeed, RAGE activation is associated with enhanced TRPV1 channel gating in models of diabetic neuropathy, which could conceivably contribute to the electrophysiological effects of HMGB1 in the present study." (PMID 34621188, 2021). "subjected KKAy mice to intermittent hypoxia to establish a diabetic neuropathy model and found that the protein expression levels of HMGB1 and TLR4 were increased and neuronal apoptosis was exacerbated." (PMID 37065747, 2023). "As a proinflammatory mediator, HMGB1 is involved in diabetic neuropathy by binding with RAGE and TLR4 and regulating autophagy." (PMID 37065747, 2023). "Recent studies illustrated roles for HMGB1 in painful diabetic neuropathy, as treatment of diabetic mice or rats with the HMGB1 inhibitor, glycyrrhizin, improved mechanical and thermal pain threshold." (PMID 35562970, 2022). "This requires confirmation, as does the contribution of HMGB1–RAGE–TRPV1 to altered pain behaviour in diabetic neuropathy in vivo." (PMID 29930087, 2018). "In diabetic neuropathy, 31 genes were studied in a single year, for example, HMGB1, IGFBP5 and SERPINF1 (PEDF)." (PMID 28761062, 2017). "Diabetic neuropathy increases BBB permeability owing to HMGB1 levels." (PMID 37863934, 2023). "The aim of the current work was to uncover the anti-allodynic and neuroprotective effects of memantine in a model of mouse diabetic neuropathy and its ameliorative effect on the high-mobility group box-1 (HMGB1)/toll-like receptor 4 (TLR4)/nuclear factor-k B (NF-kB) inflammatory axis." (PMID 33915770, 2021). "We investigated whether blocking of HMGB1 can reduce pain and inflammation in diabetic neuropathic animals to further understand the role of HMGB1 in diabetic neuropathy." (PMID 32019145, 2020). "In the current study, we examined whether glycyrrhizin mediated inhibition of HMGB1 is beneficial in alleviating pain in diabetic neuropathy." (PMID 32019145, 2020). "Therefore, like BDNF, blockage of the HMGB1/RAGE/NF-κB signaling pathway might represent a novel therapeutic strategy in the treatment of diabetic neuropathy." (PMID 31165005, 2019). "Therefore, we explored whether the acetylation of spinal HMGB1 was altered in diabetic neuropathy." (PMID 32019145, 2020). "In addition, another HMGB1‐specific inhibitor, glycyrrhizin reverses the upregulation of HMGB1 and its receptors (TLR4 and CXCR4) in mice with diabetic neuropathy, improving mechanical and thermal pain threshold in these animals." (PMID 35706377, 2022). "Our study shows that the release of HMGB1 might be involved in the activation of JNK pathways and blocking the release of HMGB1 by GLC may impede pain through alterations in CXCR4 mediated pain pathways, which could be an advantageous therapeutic approach for diabetic neuropathy." (PMID 32019145, 2020). "Blockade of HMGB1–RAGE-mediated neuronal sensitisation by rhVEGF-A165b in vitro supports our hypothesis that alteration of VEGF-A isoforms, for example by treatment with rhVEGF-A165b or an agent that alters VEGF-A splicing to favour VEGF-A165b may be an effective treatment for diabetic neuropathy." (PMID 29930087, 2018).
hyperlipidemia (12 papers, 2012 to 2025). "Increased hyperlipidemia-induced inflammation stimulates the extracellular release of the nuclear HMGB1, considered to be a DAMP." (PMID 36829889, 2023). "It was reported that hyperlipidemia upregulates the expression of HMGB-1 in experimentally induced hyperlipidemia." (PMID 31507457, 2019). "The major aim of this study was to investigate the change in serum HMGB1 levels and the effect of atrorvastatin on HMGB1 levels in patients with hyperlipidemia." (PMID 23226786, 2012). "This study investigated the effect of atorvastatin on serum HMGB1 levels in patients with hyperlipidemia." (PMID 23226786, 2012). "Furthermore, the upregulation of DAMPs including HMGB1 in hyperlipidemia and the downstream signaling enhances the overall pool of pro-inflammatory signals facilitating the aggravated co-morbidity of RCTI." (PMID 36738312, 2023). "A feedback loop action of HMGB1 was proposed by our group, explaining the inflammation enhancement in hyperlipidemia that might lead to the continuous long-term development of atheroma plaques." (PMID 36232476, 2022). "In the present study, we found that HMGB1 was increased in patients with hyperlipidemia." (PMID 23226786, 2012). "In conclusion, the present study showed that serum HMGB1 levels were increased in patients with hyperlipidemia, and that atorvastatin reduces serum HMGB1 levels which may be attributed to the decrease in serum lipids." (PMID 23226786, 2012). "Serum HMGB1 levels are increased in patients with hyperlipidemia which could be reduced by atorvastatin." (PMID 23226786, 2012). "This indicates that increased serum HMGB1 levels may be attributed to hyperlipidemia." (PMID 23226786, 2012). "Thus, we speculated that the anti-atherosclerotic effect of atorvastatin may be attributed to the inhibition of HMGB1 in hyperlipidemia." (PMID 23226786, 2012). "However, whether serum HMGB1 levels are increased in patients with hyperlipidemia remains unknown." (PMID 23226786, 2012).
myocarditis (12 papers, 2016 to 2024). Myocarditis is a condition that is characterized by inflammation of the heart muscle (myocardium). "HMGB1 was up-regulated in the hearts and serum of the mice with MHCα-induced myocarditis, which was associated with increased myocardial inflammation." (PMID 27026909, 2016). "Interestingly, a rapid and dramatic increase in plasma levels of HMGB1 and C3a and markedly early myocarditis and encephalitis were associated with early death post-BI+HS." (PMID 37108656, 2023). "We noted parallelism between the blood plasma HMGB1 and C3a levels with the prevalence of myocarditis and encephalitis." (PMID 37108656, 2023). "On the one hand, HMGB-1 is systemically elevated in models of myocarditis and ischemic myocardial infarction in mice." (PMID 32403440, 2020). "WB analysis revealed a higher expression of HMGB1 in myocarditis compared to myocardial controls." (PMID 39200277, 2024). "The role of HMGB1 in the pathogenesis of myocarditis has been evaluated for the first time in a mouse model of experimental autoimmune myocarditis (EAM) induced by inoculation of the cardiac myosin heavy chain (MyHC) peptide in the susceptible BALC/c mice strain." (PMID 30306212, 2019). "So far, although the exact mechanism of ER stress transmission in CVB3-induced myocarditis is still blur, we found that damage-associated molecular pattern (DAMP)-HMGB1 was robustly increased in the conditioned medium of CVB3-infected myocardiocytes (data not shown)." (PMID 28176833, 2017). "Importantly, our results suggest that myocarditis might promote regeneration at least partially by stimulating HMGB1/IL-6/STAT3-dependent NGC proliferation." (PMID 39200277, 2024). "Besides, Bangert and his gorup observed considerable increases in the expression of HMGB1 and RAGE, in myocardial biopsies of patients suffering from acute myocarditis." (PMID 39170697, 2024). "Interestingly, the protein expression level of HMGB1, an alarmin that activates the IL-6/STAT3 signaling pathway, was significantly higher (1.6 folds; *** p < 0.001) in endomyocardial biopsies from patients diagnosed with myocarditis compared to controls." (PMID 39200277, 2024).
retinoblastoma (12 papers, 2017 to 2025). A malignant tumor that originates in the nuclear layer of the retina. "Previous studies have also implicated HMGB1 as a downstream of miR-665 in retinoblastoma." (PMID 34889712, 2021). "Since chemotherapeutic resistance often leads to treatment failure or a high recurrence rate, the mechanism of HMGB1 resistance in retinoblastoma has also been investigated." (PMID 33140586, 2021). "Restoration of miR-665, by directly targeting HMGB1, suppressed cell proliferation, colony formation, migration, and invasion, and induced cell apoptosis in retinoblastoma." (PMID 34073766, 2021). "The STRING database plotted their protein network, and the five proteins WEE1, SMC2, HMGB1, RRM2, and POLA1 that were most associated with the range of activity involved in tumorigenesis and retinoblastoma progression were selected from 366 genes." (PMID 34646884, 2021). "As shown in the protein network plot for retinoblastoma-related genes, SMC2, HMGB1, WEE1, RRM2, and POLA1 proteins showed an association with other proteins." (PMID 34646884, 2021). "HMGB1 is expressed in most retinoblastoma tissues, and its expression is significantly different in tissues with poor tumor differentiation and optic nerve infiltration." (PMID 33140586, 2021). "Down-regulation of HMGB1 with microRNA 34a, a tumor suppressor gene, leads to inhibition of autophagy and promotes DNA damage in the retinoblastoma cell." (PMID 28969092, 2017). "Conversely, this signaling axis is negatively regulated by the tumor-suppressive microRNA MIR34A that directly targets the HMGB1 3 untranslated region to inhibit its expression, leading to suppressed autophagy and enhanced chemotherapy-induced apoptosis in retinoblastoma." (PMID 41465435, 2025). "The enhancing effect of HMGB1 on sensitivity to radiotherapy may be related to increased expression of retinoblastoma (RB), a tumor suppressor protein." (PMID 38725632, 2024). "By activating these pathways, HMGB1 can promote cell survival, proliferation, and migration, and may contribute to the aggressive behavior of retinoblastoma cells." (PMID 37894282, 2023). "There is a significant increase in HMGB1 expression in retinoblastoma (RB) cells." (PMID 35269741, 2022). "Moreover, recent studies showed that miR-665 acts as a tumor-suppressive miRNA in retinoblastoma by directly targeting high mobility group box 1 (HMGB1)." (PMID 34889712, 2021). "In addition, recent studies showed that miR-665 acts as a tumor-suppressive miRNA in retinoblastoma by HMGB1." (PMID 34889712, 2021). "Knockdown of HMGB1 by shRNA similarly induces apoptosis in retinoblastoma cells." (PMID 28969092, 2017). "Additionally, HMGB1 may interact with other signaling pathways that are involved in retinoblastoma development and progression, such as the PI3K/AKT and MAPK/ERK pathways." (PMID 37894282, 2023). "The overexpression of miRNA‐34A or direct interference in HMGB1 expression can significantly promote apoptosis by downregulating NF‐κB expression and inhibiting chemotherapeutic drug‐induced autophagy, thereby increasing the sensitivity of retinoblastoma to chemotherapy drugs." (PMID 33140586, 2021). "Addition of miR-665 inhibitor to retinoblastoma Y79 and WERI-RB-1 cell lines increased HMGB1 and LASP1 expression at both mRNA and protein levels." (PMID 37894282, 2023). "WEE1, SMC2, HMGB1, RRM2, and POLA1 proteins were also observed to be involved in the progression and invasion of retinoblastoma; SLC24A2 and DTX4 in age-related macular degeneration; and EPHB6, EFNB3, and SHC1 in glaucoma." (PMID 34646884, 2021). "However, we did not observe the interaction between TP73-AS1 and HMGB1/RAGE pathway in Rb cells (data not shown, revealed by Western blot after TP73-AS1 overexpression)." (PMID 31015368, 2019).
Shock (12 papers, 2012 to 2023). The state in which profound and widespread reduction of effective tissue perfusion leads first to reversible, and then if prolonged, to irreversible cellular injury. "Upon exposure to the bacterial endotoxin LPS, the level of circulating HMGB1 was reduced in mice treated with DOE, which was accompanied by an improvement in their survival rate, indicating that the effects of DOE on septic shock are HMGB1-dependent." (PMID 28403838, 2017). "Our results suggest that induction of HMGB1 is important in hemorrhagic shock and resuscitation-induced acute lung inflammation." (PMID 25309129, 2014). "These investigators showed that HMGB1 was released by macrophages stimulated by lipopolysaccharide (LPS), tumor necrosis factor-α (TNF- α), and IL-1ß and that high HMGB1 was measured in plasma from patients with septic shock." (PMID 22788849, 2012). "As a late pro-inflammatory factor, the extracellular high mobility group box 1 (HMGB1) protein triggers responses that cause damage to tissues leading to the activation of the inflammatory cascade in several conditions, including lung injury and septic shock." (PMID 33569375, 2020). "Finally, in vivo work demonstrated that HMGB1 contributes to the development of lung injury after severe hemorrhage and that HMGB1-mediated lung inflammation depends on TLR4 in the early phase and on TLR2 in the late phase following hemorrhagic shock." (PMID 23696858, 2013). "Furthermore, Pannexin-1 channels, purinergic P2X7 pore, and high mobility group protein B1 (HMGB1) are required for caspase-11-mediated pyroptosis and endotoxin shock, a mechanism that seems to be independent of TLR4." (PMID 35600331, 2022).